CCDC170 (coiled-coil domain containing 170)
Description:
Plays a role in Golgi-associated microtubules organization and stabilization.
Synonyms: C6orf97; FLJ23305; bA282P11.1
Tractability: No criterion of Open Targets' tractability assessment is met for any kind of drug.
Gene: Protein-coding gene on chromosome 6 (151,494,013 to 151,621,193, forward strand). Ensembl gene ENSG00000120262.
Subcellular location: Golgi apparatus
Subcellular location (Human Protein Atlas): Golgi apparatus; Cell Junctions
Gene Ontology:
Molecular function: microtubule binding; protein binding
Biological process: microtubule cytoskeleton organization
Cellular component: ciliary basal body; Golgi apparatus
Genetic constraint (gnomAD): Loss-of-function variants: 70 observed, 73.77 expected, observed/expected ratio (o/e) 0.95, 90% interval 0.78 to 1.16. The upper end of that interval is the gene's LOEUF score, 1.16, which puts it in group 5 of 6, group 1 being the genes least tolerant of losing a copy. Missense variants: 847 observed, 853.04 expected, observed/expected ratio (o/e) 0.99, 90% interval 0.94 to 1.05. Synonymous variants: 299 observed, 313.83 expected, observed/expected ratio (o/e) 0.95, 90% interval 0.87 to 1.05.
Homologues: Orthologues: chimpanzee CCDC170 (99% identical), macaque CCDC170 (86% identical), pig CCDC170 (82% identical), dog CCDC170 (82% identical), guinea pig CCDC170 (77% identical), rat Ccdc170 (70% identical), rabbit CCDC170 (70% identical), mouse Ccdc170 (68% identical), tropical clawed frog ccdc170 (54% identical), Drosophila melanogaster CG43338 (21% identical), Caenorhabditis elegans C27D6.1 (16% identical), zebrafish ccdc170 (11% identical).
Diseases named in the same sentence as CCDC170 in open-access papers:
CCDC170 is named in the same sentence as 20 diseases in open-access papers, as found by Europe PMC text mining. Sharing a sentence is not in itself a finding about the gene and the disease. The quoted sentences say what the papers report.
breast carcinoma (31 papers, 2010 to 2025). "It has been reported that the polymorphism of the CCDC170 gene correlates with breast cancer susceptibility." (PMID 33557149, 2021). "Multiple studies have found that CCDC170 plays an important role in breast cancer, and multiple genome-wide linkage analyses have shown that CCDC170 is one of the genes most strongly linked to BMD." (PMID 33785515, 2021). "Genome-wide association studies have revealed that single-nucleotide polymorphisms residing in the intergenic region between estrogen receptor 1 (ESR1) and coiled-coil domain containing 170 (CCDC170) at 6q25.1 are associated with breast cancer risk." (PMID 33291081, 2020). "Genome-wide association studies have revealed that multiple single-nucleotide polymorphisms in the intergenic region between estrogen receptor 1 and coiled-coil domain containing 170 (CCDC170) are associated with breast cancer risk." (PMID 33291081, 2020). "Higher CCDC170 expression was associated with a better prognosis in breast cancer patients, and the expression of IRE1α, XBP1s and ERα correlated with the expression of CCDC170." (PMID 33291081, 2020). "Several single-nucleotide polymorphisms around human CCDC170 have been identified as important breast cancer risk indicators in Chinese women." (PMID 33291081, 2020). "Allele-specific expression studies suggest that breast cancer SNPs are more strongly associated with CCDC170 expression." (PMID 30642363, 2019). "Previous GWAS and candidate approaches have identified multiple genetic variants at CCDC170/ESR1 to be associated with breast cancer as well as mammographic density." (PMID 26036842, 2015). "Further functional investigations of CCDC170 and 6q25.1 are warranted to fully reveal the mechanisms underlying the observed association with risk of breast cancer." (PMID 25116933, 2014). "Logistic regression analysis revealed that the minor rs9383935 A allele of CCDC170 was significantly associated with an increased risk of breast cancer in an additive model (per-allele OR = 1.38, 95% CI: 1.20 to 1.57, P = 2.21 × 10-6)." (PMID 25116933, 2014). "After correction for multiple testing (n = 7), rs9383935 and rs2046210 of CCDC170 were still significantly associated with breast cancer risk (P < 0.007)." (PMID 25116933, 2014). "In addition, genetic and epigenetic deviations in loci affiliated with the Golgi apparatus, such as CCDC170 (Coiled–Coil Domain Containing 170), have been entwined with susceptibilities to breast cancer." (PMID 37762375, 2023). "The CCDC170 gene affects both breast cancer risk and progression." (PMID 35563727, 2022). "Our study showed that higher CCDC170 expression is associated with a better prognosis in breast cancer patients and that CCDC170 may promote apoptosis through the IRE1α pathway." (PMID 33291081, 2020). "Indeed, higher CCDC170 expression has been associated with a better prognosis in certain breast cancer subtypes, but with a poorer prognosis in others." (PMID 33291081, 2020). "Another interesting illustration is provided by the poorly studied breast cancer gene CCDC170, which encodes for one of the most charged and acidic human proteins but also appears to have some structural role in maintaining the organization of Golgi-associated microtubules." (PMID 30226837, 2018). "The results of this study suggest that the functional variant rs9383935, located at the 3' UTR of CCDC170, may be one candidate of the causal variants at 6q25.1 that modulate the risk of breast cancer." (PMID 25116933, 2014). "Taken together, these findings suggest that the variant rs9383935 may modulate individual susceptibility to breast cancer, possibly through regulating miR-27a inhibition of CCDC170 expression." (PMID 25116933, 2014). "Our database identified well-known fusion genes that are commonly associated with breast cancer, such as ESR1::CCDC170, and revealed previously unreported fusion genes, including TPTE2::MRPS31P2 and LHFPL5::CLPSL1." (PMID 41213951, 2025).
breast carcinoma (continued). "CCDC170 is a coiled-coil domain-containing protein that affects apoptosis of breast cancer cells through the IRE1 pathway, and a few studies have reported that ESR1-CCDC170 fusion is a carcinogenic fusion driver for breast cancer." (PMID 37024829, 2023). "CCDC170 stands out as a critical genetic component interlinked with the Golgi system with profound effects on breast cancer proliferation." (PMID 37762375, 2023). "The presence of the ESR1 fusions with AKAP12, ARMT1 and CCDC170 (exon 2 to exon 11) was evaluated in breast cancer tissue samples from 732 breast cancer patients." (PMID 35151276, 2022). "Li and colleagues provided detailed evidence supporting the function of ESR1-e2>CCDC170 in promoting breast cancer cell survival and endocrine resistance both in vitro and in xenograft models." (PMID 36686845, 2022). "In this study, the characteristics of an ER-positive molecular subtype in CCDC170-subtype breast cancer were identified, and genes specifically regulated in E:C BRCA were identified and screened for BRCA-related signaling pathways." (PMID 33557149, 2021). "Taken together, the CCDC170 fusion-positive BRCA showed a mutually exclusive relationship with the basal-type breast cancer cells." (PMID 33557149, 2021). "CCDC170 more noticeably induced apoptosis (and upregulated IRE1α) in breast cancer cells under endoplasmic reticulum stress." (PMID 33291081, 2020). "In the present work, we first used a gene chip to identify genes that were differentially expressed upon ectopic CCDC170 expression in MCF7 breast cancer cells." (PMID 33291081, 2020). "While the physiological function of CCDC170 has not been well understood, previous studies have suggested that CCDC170 expression alters the prognosis of breast cancer patients." (PMID 33291081, 2020). "We performed microarray and bioinformatics analyses to identify genes that were induced upon CCDC170 overexpression, and confirmed our findings by evaluating paraffin-embedded breast cancer tissues and conducting cellular assays." (PMID 33291081, 2020). "Though these data have highlighted the importance of the CCDC170 gene and its fusion protein in breast cancer, the pathobiology and clinical relevance of CCDC170 have remained unclear." (PMID 33291081, 2020). "In CCDC170-overexpressing MCF7 breast cancer cells, microarray analyses revealed that inositol-requiring enzyme 1 (IRE1) was the most elevated gene in enriched pathways." (PMID 33291081, 2020). "The human cDNA microarray analysis in the present study has provided clues into the functions of CCDC170 in breast cancer." (PMID 33291081, 2020). "We also observed that either stable or transient CCDC170 overexpression clearly inhibited the growth of breast cancer cells." (PMID 33291081, 2020). "Our DEG analysis in MCF7 breast cancer cells revealed that IRE1 was upregulated in CCDC170-overexpressing cells." (PMID 33291081, 2020). "Western blotting and immunofluorescence analyses indicated that ERα, IRE1α and XBP1s levels correlated with CCDC170 levels in MCF7 breast cancer cells." (PMID 33291081, 2020). "Our immunohistochemical analyses demonstrated that CCDC170 and XBP1s were preferentially expressed in ERα+ breast cancer tissues, consistent with previous observations." (PMID 33291081, 2020). "Next, we used immunohistochemistry to assess the localization of CCDC170 in paraffin-embedded breast cancer tissues, and found that it was expressed in the cytoplasm." (PMID 33291081, 2020). "To investigate the prognostic value of CCDC170, IRE1α and XBP1s in breast cancer, we used immunohistochemistry to assess the expression of these proteins in 100 patients with invasive ductal carcinoma." (PMID 33291081, 2020). "CCDC170 was found to be co-expressed with ESR1 in breast cancer tissues, and an ESR1-CCDC170 rearrangement was discovered in luminal B breast tumors." (PMID 33291081, 2020).
breast carcinoma (continued). "The broader involvement and clinical relevance of CCDC170 in the pathogenesis of breast cancer will be the focus of future investigations." (PMID 33291081, 2020). "This rearrangement leads to a truncated CCDC170 protein which, when introduced into ER+ breast cancer cells, leads to increased cell motility, anchorage-independent growth, reduced endocrine sensitivity, and enhanced xenograft tumor formation." (PMID 30642363, 2019). "CCDC170 is only 133 kb away from estrogen receptor 1 (ESR1), and the closest SNPs to CCDC170 are associated with breast cancer and endometriosis risk." (PMID 30149579, 2018). "Other genes present in our MINT gene signature include XPB1, AGR3, CCDC170 and TFF3 that were reported as being associated with breast cancer." (PMID 28241739, 2017). "The trans-acting SNPs in CCDC170 are located in the region on chromosome 6q25 in which a fusion event has been reported in breast cancer between the second exon of ESR1α to the sixth and seventh exon of CCDC170." (PMID 28152060, 2017). "Additional studies are needed to validate our findings and extend the role of CCDC170 in the etiology of breast cancers." (PMID 25116933, 2014). "Subsequently, one intronic variant, rs3757318 in CCDC170, and another intronic rs9383951 in ESR1, were also found to be associated with breast cancer risk." (PMID 25116933, 2014). "Among these SNPs, rs2046210, located between coiled-coil domain containing 170 (CCDC170, also called C6orf97) and estrogen receptor 1 (ESR1) at 6q25.1, was first reported to be associated with the risk of breast cancer in Chinese populations." (PMID 25116933, 2014). "Moreover, a previous study demonstrated that CCDC170 wasfused to ESR1 in breast cancer (Veeraraghavan etal., 2014)." (PMID 38626574, 2024). "CCDC170: CCDC170 affects breast cancer apoptosis through IRE1 pathway." (PMID 37468832, 2023). "While the function of ESR1 in breast cancer has been well studied, that of CCDC170 remains elusive." (PMID 33291081, 2020). "We speculated that CCDC170 might have important functions and clinical significance in breast cancer, considering its relationship with ESR1." (PMID 33291081, 2020). "We also examined the effects of stably overexpressing CCDC170 in MCF7 breast cancer cells." (PMID 33291081, 2020). "When cases in TCGA were stratified by subtype, CCDC170 mRNA levels were higher in the luminal A and luminal B subtypes, but were lower in the human epidermal growth factor receptor 2 (Her2)-positive and Basal-like breast cancer subtypes." (PMID 33291081, 2020). "Specifically, the CCDC170 rs9383935 showed the most prominent effect of any other variants of ESR1 or rs2046210, which provides new evidence for the role of the 6q25.1 region in breast cancer susceptibility." (PMID 25116933, 2014). "In the present study, we genotyped six potentially functional single-nucleotide polymorphisms (SNPs) within the CCDC170 and ESR1 gene regions at 6q25.1 and accessed their associations with risk of breast cancer in a study of 1,064 cases and 1,073 cancer-free controls in Chinese women." (PMID 25116933, 2014). "Other genes, such as ESR1 (logFC 6.02); GATA3 (logFC 3.88); ERBB4 (logFC 3.0); AR (logFC 2.94); CCDC170 (logFC 2.79); MAPT (logFC 2.45); PGR (logFC 2.91); PIP (logFC 5.42) in immunoglobulin G-binding protein from this cluster were closely associated with breast cancer progression." (PMID 32182819, 2020). "Furthermore, other genes at this locus including ARMT1, CCDC170, and RMND1 may also be candidates for an effect on breast cancer risk." (PMID 30642363, 2019). "For example, ESR1::CCDC170 has been detected in 6%–8% of Luminal B breast cancers, a more aggressive and endocrine-resistant subtype of HR+/HER2‒ breast cancer, and has been shown to promote increased tumor invasiveness and endocrine resistance." (PMID 41213951, 2025).
breast carcinoma (continued). "Although little is known about the role of CCDC170 in UF, it is recurrently fused with the ESR1 gene in ~14 % of ER+ breast cancers, and patients with such fusion have worse clinical outcomes." (PMID 38326302, 2024). "When first described, ESR1-e2>CCDC170 in ER+ breast cancer cells led to enhanced growth and reduced sensitivity to tamoxifen suggesting a role for ESR1-e2>CCDC170 in ET resistance." (PMID 36686845, 2022). "It is noteworthy that up to date, only few ESR1 fusions (ESR1-e2>CCDC170, ESR1-e4>CCDC170, ESR1-e5>CCDC170, ESR1-e6>NOP2, ESR1-e6>AKR1D1, ESR1-e6>POLH) were detected in primary breast cancer samples." (PMID 36686845, 2022). "Through analysis of RNA-sequencing data in breast cancer, recurrent intragenic fusions of 5′ end of ESR1 and the 3′ ends of AKAP12, ARMT1 or CCDC170 amongst other genes have been identified." (PMID 35151276, 2022). "In breast cancer (BC), recurrent fusion genes of estrogen receptor alpha (ESR1) and AKAP12, ARMT1 and CCDC170 have been reported." (PMID 35151276, 2022). "To further explore the relationship of CCDC170 with IRE1α, XBP1s and ERα, we conducted a series of in vitro assays in MCF7 breast cancer cells in which CCDC170 was overexpressed or silenced." (PMID 33291081, 2020). "In the present study, the positive correlation between CCDC170 and IRE1 levels in our microarray analysis was validated at both the mRNA and protein levels in breast cancer tissues and cells." (PMID 33291081, 2020). "Thus, CCDC170 may have considerable potential as a therapeutic target for breast cancer." (PMID 33291081, 2020). "In breast cancer tissues, IRE1 expression correlated positively with CCDC170 and X-box binding protein 1 expression at both the mRNA and protein levels." (PMID 33291081, 2020). "Next, we determined the correlation between CCDC170 and IRE1 expression in breast cancer tissues from The Cancer Genome Atlas (TCGA) and the Gene Expression Omnibus (GEO)." (PMID 33291081, 2020). "We further analyzed the relevance of CCDC170, IRE1 and XBP1 expression to breast cancer prognosis in two independent cohorts (TCGA and GEO), and found that higher expression of CCDC170, IRE1 and XBP1 correlated with better OS in GEO." (PMID 33291081, 2020). "In our study, expression of ESR1 fused to exons 2 and exon 8 of CCDC170 was found in mammary epithelial tissues derived from women without diagnosis of breast cancer, and in cases with (benign) fibroadenomas, respectively." (PMID 35151276, 2022). "To identify genes that could be induced by CCDC170, we transfected MCF7 breast cancer cells with either a pCMV-N-Flag-CCDC170 vector or a pCMV-N-Flag control vector." (PMID 33291081, 2020). "The second variant at 6q25.1 (rs60705924) is located in CCDC170/ESR1 region, a well-established breast cancer locus, but its putative functions are not well defined." (PMID 26036842, 2015). "Furthermore, whether CCDC170 was overexpressed transiently (P = 0.001) or stably (P = 0.003) in MCF7 breast cancer cells, the cell viability was significantly lower than that of the control group in a 3-(4,5-dimethylthiazol-2-yl)-2,5-diphenyltetrazolium bromide (MTT) assay." (PMID 33291081, 2020).
endometriosis (8 papers, 2017 to 2024). The growth of functional endometrial tissue in anatomic sites outside the uterine body. "We conducted a GWA meta-analysis of ∼7 million SNPs in 17,045 endometriosis cases and 191,596 controls, confirmed 9 out of 11 previously reported European risk loci, and identified five new genomic regions in or near CCDC170, SYNE1, FSHB, FN1 and 7p12.3 harbouring endometriosis risk loci." (PMID 28537267, 2017). "Similarly, potential endometrial-specific endometriosis-associated mQTLs lie in a predicted promoter for CCDC170 and enhancer regions that may mediate regulatory effects on multiple genes in the chromosome 6q25.1–6q25.2 risk region." (PMID 37587191, 2023). "In primary meta-analysis, they identified two SNPs at the locus rs71575922 in SYNE1 and rs1971256 in CCDC170, located in endometriosis up- and downstream of ESR1, respectively." (PMID 32370117, 2020). "Five additional new loci significantly associated with the risk of endometriosis (p < 5 × 10−8) of genes involved in sexual steroid hormone pathways (FN1, CCDC170, ESR1, SYNE1 and FSHB) were identified, for a total of 16 genomic regions associated with endometriosis risk in one or more populations." (PMID 32143537, 2020). "In addition to replicating previously reported loci, we identify five novel loci significantly associated with endometriosis risk (P<5 × 10−8), implicating genes involved in sex steroid hormone pathways (FN1, CCDC170, ESR1, SYNE1 and FSHB)." (PMID 28537267, 2017). "In addition to replicating 9 of the 11 previously reported European risk loci, this GWA meta-analysis identified 5 novel loci significantly associated with endometriosis risk (P<5 × 10−8), implicating genes involved in sex steroid hormone pathways (FN1, CCDC170, ESR1, SYNE1 and FSHB)." (PMID 28537267, 2017).
breast tumors (4 papers, 2014 to 2020). "In addition, CCDC170 was found to be tightly co-expressed with ESR1 in breast tumor biopsies and cells." (PMID 33291081, 2020).